ELF3 (E74 like ETS transcription factor 3)
Diseases named in the same sentence as ELF3 in open-access papers (continued):
Sharing a sentence is not in itself a finding about the gene and the disease.
bladder urothelial carcinoma (2 papers, 2023). "Somatic mutation or reduced expression of ELF3 was reported in uterine cervical adenocarcinomas, urothelial bladder carcinoma, and oral SCC." (PMID 36951594, 2023). "However, in bladder urothelial carcinoma, overexpressing ELF3 repressed tumor-sphere formation despite antagonizing EMT." (PMID 36864480, 2023).
cervical intraepithelial neoplasia (2 papers, 2023 to 2024). "In the study of HPV 16 positive cervical intraepithelial neoplasia, downregulation of ELF3 has been found to inhibit the squamous differentiation of human cervical dysplasia cells in vitro." (PMID 39572025, 2024).
colorectal neoplasm (2 papers, 2019 to 2020). A benign or malignant neoplasm that affects the colon or rectum. "We showed that ELF3 exhibits mutually exclusive patterns of expression with CTNNB1/ β-catenin across colorectal tumour panels and that ELF3 is an antagonist of Wnt/β-catenin and RAS signalling-induced EMT." (PMID 30148686, 2019).
esophageal adenocarcinoma (2 papers, 2024 to 2025). A malignant tumor with glandular differentiation arising predominantly from Barrett mucosa in the lower third of the esophagus. "In a murine esophageal adenocarcinoma model, the ELF3 super-enhancer was up-regulated by nuclear receptor transcription factor peroxisome proliferator activating receptor γ (PPARγ) which is induced by a high-fat diet." (PMID 41425714, 2025). "For instance, in esophageal adenocarcinoma, SEs that are specific to this type of cancer regulate the overexpression of pro-carcinogenic transcription factors like ELF3, KLF5, GATA6, and EHF." (PMID 38443991, 2024).
esophageal squamous cell carcinoma (2 papers, 2023 to 2024). Esophageal squamous cell carcinoma (ESCC) is a type of esophageal carcinoma (EC) that can affect any part of the esophagus, but is usually located in the upper or middle third. "Among these CRLs, esophageal squamous cell carcinomas were reported to be suppressed by lncRNA LINC00886 through the SIRT7/ELF3/miR-144 pathway." (PMID 36674979, 2023). "In esophageal squamous cell carcinoma (ESCC), SIRT7 deacetylates the promoter of E74 like ETS transcription factor 3 (ELF3), rendering it no longer able to suppress miR-144-3p, a posttranscriptional suppressor of zinc finger E-box binding homeobox 1/2 (ZEB1/2) EMT markers." (PMID 37676263, 2024).
gallbladder cancer (2 papers, 2020 to 2024). "The ELF3, ETS-domain transcription factor, identified as significantly mutated gallbladder cancer gene was altered in 21% of samples (34/160)." (PMID 32839463, 2020). "Here the authors perform a genomic analysis of gallbladder cancers in patients from countries with high incidence (South Korea, India and Chile) and identify ELF3 and other significantly mutated genes not previously associated with gallbladder cancer." (PMID 32839463, 2020).
head and neck squamous cell carcinoma (2 papers, 2024). A squamous cell carcinoma that arises from any of the following anatomic sites: lip and oral cavity, nasal cavity, paranasal sinuses, pharynx, larynx, and salivary glands. "Compared with HPV16-negative head and neck squamous cell carcinoma (HNSCC), the upregulation of ELF3 expression is observed in HPV16-positive HNSCC from the Gene Expression Omnibus (GEO)." (PMID 39572025, 2024). "ELF3 and CCNE2 presented overexpression patterns in head and neck squamous cell carcinoma." (PMID 39572025, 2024).
lung squamous cell carcinoma (2 papers, 2020 to 2021). "However, given that the expression of ELF3 is upregulated in several K-Ras mutant LUADs and lung squamous cell carcinomas (LSCCs), whether auranofin has therapeutic potential to repress ELF3 through inhibition of PKCί activity in EGFR mutant LUAD remains unclear." (PMID 34830169, 2021).
metastatic cancer (2 papers, 2022 to 2023). A carcinoma which has spread from the original site of growth to another anatomic site. "ELF3 is expressed in some high grade cancers and there is evidence for ELF3 amplification in metastatic cancers." (PMID 35472129, 2022). "Given that the degree of knockdown was similar in both cell lines, this result implies that advanced grade PC3 metastatic cancer‐derived cells may already have upregulated compensatory pathways and alternative mechanisms to cope with ELF3 knockdown." (PMID 35472129, 2022). "Results revealed a higher Mesenchymal markers in primary cancer cells (e.g., NCAM1, LAMB1, SERPINE1, TCF4, VIM, ZEB1, and ZEB2) and a higher Epithelial markers in metastatic cancer cells (e.g., CDH1, CLDN4, ELF3, EPCAM, KRT18, KRT7, and KRT8)." (PMID 37202394, 2023).
pancreatic ductal adenocarcinoma (2 papers, 2019 to 2023). An infiltrating adenocarcinoma that arises from the epithelial cells of the pancreas. "To evaluate if ELF3 directly regulate IRF6 expression or not, we firstly analyzed the only available chip-seq data of ELF3 antibody in the pancreatic ductal carcinoma, which obtained from the online website of Cistrome." (PMID 31019894, 2019).
rheumatoid arthritis (2 papers, 2016 to 2022). A chronic, systemic autoimmune disorder characterized by inflammation in the synovial membranes and articular surfaces. "Interestingly, IκBζ was also found to be involved in regulating IL17A and TNF‐induced transcription factor, ELF3 in synovial fibroblasts collected from rheumatoid arthritis (RA) and OA patients." (PMID 36245291, 2022).
Alzheimer disease (1 paper, 2025). A progressive, neurodegenerative disease characterized by loss of function and death of nerve cells in several areas of the brain leading to loss of cognitive function such as memory and language. "Using Mpipi‐T, we analyze three key proteins postulated to exhibit LCST: Alzheimer's disease‐associated hTau40, stress granule‐binding Pab1, and circadian clock regulator ELF3." (PMID 40944421, 2025).
autism (1 paper, 2022). Persistent deficits in social interaction and communication and interaction as well as a markedly restricted repertoire of activity and interest as well as repetitive patterns of behavior. "The fivefold downregulated MPO, TMCC3, MMP8, CA1, and ELF3 genes and the fivefold upregulated MTRNR2L8 gene can be considered for the early identification of autism patients among Saudis." (PMID 35215271, 2022).
brain tumors (1 paper, 2012).
colon cancer (1 paper, 2022). "ELF3 is closely associated with bladder, ovarian, biliary tract, gastric, cervical, breast, prostate, lung, liver, and colon cancer and increases cell proliferation, invasion, and migration." (PMID 35845594, 2022).
COVID-19 (1 paper, 2023). A disease caused by infection with severe acute respiratory syndrome coronavirus 2. "In summary, SPDEF and ELF3 were shared between goblet and squamous cells in severe COVID-19, and S100A9 was co-upregulated." (PMID 37936693, 2023). "Furthermore, NR2F6, SPDEF, and ELF3 were found to be activated in squamous cells in patients with severe COVID-19, and this activity was also shared with goblet cells." (PMID 37936693, 2023). "For example, RFX2 and RFX3 showed high activity in ciliated cells regardless of disease severity, while XBP1, NR2F6, SPDEF, and ELF3 were preferentially activated in goblet cells in patients with severe COVID-19, and KLF5 and STAT2 were coactivated in patients with mild/moderate COVID-19." (PMID 37936693, 2023). "For example, compared to activated STAT2 and KLF5 in mild/moderate goblet cells, SPDEF, ELF3, XBP1, and NR2F6 were found activated in patients with severe COVID-19." (PMID 37936693, 2023). "Similarly, SPDEF and ELF3 were found to be activated in squamous cells, and CEBPD and FOS were shared between CD14 and CD14 monocytes in severe COVID-19." (PMID 37936693, 2023). "For squamous cells, there were no activated regulons in SPDEF and ELF3 in mild/moderate COVID-19, but they were activated in severe COVID-19." (PMID 37936693, 2023). "In goblet cells, STAT2 and KLF5 were highly activated and upregulated in many genes with mild/moderate COVID-19, such as ISGs (PARP14 and IFI44L), whereas ELF3, SBP1, NR2F6, and SPDEF were preferentially activated in severe COVID-19 to regulate the expression of their targets." (PMID 37936693, 2023).
cutaneous melanoma (1 paper, 2021). A primary melanoma arising from atypical melanocytes in the skin. "According to the results of the multivariate Cox regression analysis, three of the seventeen m6A RNA methylation regulators were proved to be the potential prognostic factors of cutaneous melanoma, including ELF3, ZC3H13, and WTAP." (PMID 34291082, 2021).
diabetes insipidus (1 paper, 2019). A disorder characterized by excretion of large amounts of urine, accompanied by excessive thirst. "In addition, our study also uncovered a potential new mechanism for lithium-induced diabetes insipidus via reducing the gene expression level of the transcription factor Elf3." (PMID 31681015, 2019).
endometrial cancer (1 paper, 2021). Primary or metastatic malignant neoplasm involving the endometrium (mucous membrane that lines the endometrial cavity). "A high expression of ELF3 mRNA was found in 136 NSCLCs cell lines in the Cancer Cell Line Encyclopedia (CCLE) database similar to that observed in breast, urinary tract, or ovarian and endometrial cancers." (PMID 34830169, 2021).
Erythema (1 paper, 2025). Redness of the skin, caused by hyperemia of the capillaries in the lower layers of the skin. "Indeed, adult elf3 mutants of both sexes presented a range of clinical pathologies such as abnormal swimming behavior indicative of impaired swim bladder buoyancy, ulcer development on the body flank, or erythema." (PMID 41147741, 2025).
inflammatory bowel disease (1 paper, 2017). A spectrum of small and large bowel inflammatory diseases of unknown etiology. "Several IEC signature TFs have known associations with human Inflammatory Bowel Diseases (IBD), including SMAD7, CEBPG, STAT3, XBP1, HNF4A, ELF3, IRF1, and NFκB components IKBKB, IKBKG, and NFKBIZ." (PMID 28850571, 2017).
lymph node metastases (1 paper, 2016). "The results showed that ELF3 may sufficiently assess the lymph node metastases of CRC." (PMID 27827952, 2016). "Our data indicate that ELF3 expression in NSCLC tissues is associated with lymph node metastasis and clinical stage; however, its expression in PBMCs is not correlated with lymph node metastasis." (PMID 27827952, 2016).
metastasis (1 paper, 2016). The spread or migration of cancer cells from one part of the body (where they first appeared) to another. "The expression of CK7 and ELF3 in tumor tissues and EGFR in PBMCs was associated with lymph node metastasis (all p < 0.05)." (PMID 27827952, 2016).
metastatic colorectal cancer (1 paper, 2021). "Here, we found that GRHL2, ELF3, and OVOL1 were overexpressed in the CTC lines compared with SW620 cells (metastatic colorectal cancer cell line), particularly GRHL2." (PMID 34771571, 2021).
mucinous tumors of the ovary (1 paper, 2015). "This study provides a basis for understanding the diverse pathways targeted by somatic mutation in mucinous tumors of the ovary, although further functional work is required to elucidate the role of novel, less commonly affected genes with conflicting roles in the literature, such as ELF3 and KLF5." (PMID 26257827, 2015).
nephrogenic diabetes insipidus (1 paper, 2019). Nephrogenic diabetes insipidus (NDI) is characterized by polyuria with polydipsia, recurrent bouts of fever, constipation, and acute hypernatremic dehydration after birth that may cause neurological sequelae. "Our data provide a potential explanation to lithium-induced nephrogenic diabetes insipidus where lithium reduces Elf3 and hence AQP2 abundance." (PMID 31681015, 2019).
oesophageal cancer (1 paper, 2023). "The top GPR176-correlated genes (PDPH, KIREL1, CLEC12A-AS1, CERCAM, IKBIP, LOX, COL5A2 and ELF3) were more highly expressed in oesophageal cancer than in normal tissue (p < 0.05), but the converse was true for C9orf152 and MT-TP (p < 0.05)." (PMID 37584712, 2023).
psoriasis (1 paper, 2011). An autoimmune condition characterized by red, well-delineated plaques with silvery scales that are usually on the extensor surfaces and scalp. "For instance, among transcripts increased significantly in human psoriasis, we identified 26 transcripts associated with the “epidermis development” (GO:0008544) gene ontology term (e.g., KRT16, KRT17, ELF3)." (PMID 21483750, 2011).
small cell lung carcinoma (1 paper, 2021). Small cell lung cancer (SCLC) is a highly aggressive malignant neoplasm, accounting for 10-15% of lung cancer cases, characterized byrapid growth, and early metastasis. "However, small cell lung cancer showed lower expression of ELF3 mRNA than NSCLC." (PMID 34830169, 2021).
thymic epithelial tumors (1 paper, 2024). "High methylation in cg07154254 (ELF3) was related to longer overall survival in patients with thymic epithelial tumors." (PMID 39219440, 2024).
thyroid tumor (1 paper, 2026). A benign or malignant neoplasm affecting the thyroid gland. "Our findings suggest that miR-1179 is a tumor suppressor gene and that its loss may contribute to thyroid tumor progression by promoting the expression of ELF3, NOTCH3, and CX3CL1." (PMID 42121903, 2026).
tongue cancer (1 paper, 2021). A malignant neoplasm affecting the tongue. "We therefore investigated genomic alteration in the ESE domain of the EHF and ELF3 genes by sequencing, after genomic DNA was isolated from specimens of human patients with tongue cancer." (PMID 33712555, 2021).
viral infection (1 paper, 2025). "Our experiments revealed that viral infection promoted the nuclear translocation of ELF3, a member of the ETS transcription factor family, thereby enhancing TRIM22 expression and contributing to its antiviral effects." (PMID 40162781, 2025). "In this loop, ELF3 rapidly translocates to the nucleus to activate TRIM22 gene expression after viral infection, while TRIM22 activates IFN-β antiviral signaling through K63-linked polyubiquitination of MAVS." (PMID 40162781, 2025).
tumor (100 papers, 2006 to 2026). "IHC of serial sections revealed that high expressions of CRC (ELF3/EHF/TGIF1-High) were closely associated with high proliferative activity in tumor tissue and poor prognosis on patients with LUAD." (PMID 33070167, 2020). "While the inactivating mutations in ELF3 would suggest a tumour suppressive role, the functional significance of these mutations in disease pathogenesis has yet to be directly established in cell line or animal models." (PMID 30200227, 2018). "Although analyzed separately, these additional samples corroboratedthe mutations above and highlighted additional recurrent mutations in theBRCA2, MLL3, APC,NF1, and ELF3 tumor-suppressor genes." (PMID 28297679, 2017). "ELF3, an m6A “reader” with cancer-specific expression/mutation patterns, demonstrates drug sensitivity correlations, suggesting dual roles in the therapeutic response and tumor progression." (PMID 40867324, 2025). "Further investigation into the underlying molecular mechanisms by which ELF3 exerts its tumour‐suppressive effects may provide valuable insights into the development of targeted therapies for OC and other cancers with aberrant ELF3 expression." (PMID 38520216, 2024). "Loss of ELF3 mRNA and protein expression has been associated with a worse prognosis in OC, suggesting that ELF3 may act as a tumour suppressor in this context." (PMID 38520216, 2024). "Such context-specific associations may underlie lineage-restricted roles of ELF3 as a tumor suppressor or an oncogene, depending on cancer cell lineage and/or differentiation status." (PMID 36864480, 2023). "To determine whether ELF3 was associated with a NE phenotype in PCa, we treated primary prostate epithelial cultures derived from tumours with the HDAC inhibitor vorinostat." (PMID 35472129, 2022). "Our results implicated that ELF3 in LUAD tumor cells may serve as a novel therapeutic target to prevent tumor growth." (PMID 33144684, 2021). "ELF3 overexpression was significantly associated with tumor size (p < 0.05)." (PMID 29523781, 2018). "Furthermore, loss of ELF3 mRNA and protein expression is associated with poorer outcome in OC, collectively suggesting a tumour suppressive role." (PMID 30200227, 2018). "Taken together, these data suggested that ELF3 may serve as a marker associated with poor prognosis and a high risk of tumor metastasis in HCC." (PMID 29523781, 2018). "All cells (normal cells and tumor cells) are involved, and ELF3 expression was normalized by reads in each cell." (PMID 41498327, 2026). "The novel findings regarding candidate genes such as CFI and ELF3 not only enhance our understanding of tumor biology but also pave the way for precision diagnosis and targeted therapy." (PMID 40867324, 2025). "Studies have demonstrated that ELF3 expression levels are significantly correlated with tumour metastatic potential." (PMID 40996711, 2025). "P03 also has mutations in MTOR and ELF3, while P04 has mutations in FGFR1, and P05 has mutations in PIK3CA and NTRK1–genes involved in tumor growth and survival." (PMID 41012124, 2025). "To clarify the ELF3 in the anti-tumor effects of Huaier mediated by DLEU2/MiR-212-5p, we cotransfected DLEU2 siRNA and pcDNA3.1-ELF3 or DLEU2 siRNA and vector control into A549 cells." (PMID 38169645, 2024). "Positive staining of GLUT1 and LDHA was reduced in tumor tissues formed by C666-1 cells with ELF3 knockdown." (PMID 39219440, 2024). "Collectively, the DLEU2/miR-212-5p/ELF3 pathway mediates the anti-tumor effects of Huaier by ultimately regulating proteins involved in migration and invasion." (PMID 38169645, 2024). "On the other hand, knocking down ELF3 expression in OC cell lines induces epithelial to mesenchymal transition (EMT), a phenomenon associated with enhanced tumour progression and metastasis." (PMID 38520216, 2024).